RET (ret proto-oncogene)
Diseases named in the same sentence as RET in open-access papers (continued):
Sharing a sentence is not in itself a finding about the gene and the disease.
medullary thyroid carcinoma (continued). "The condition arises from a RET (rearranged during transfection variant) gene variant on chromosome 10q11.2, which often results in medullary thyroid carcinoma, typically diagnosed before 35 years." (PMID 38802890, 2024). "Clinical trials on RET inhibitors for RET gene fusion and medullary thyroid cancer with a positive RET gene mutation are ongoing." (PMID 38791384, 2024). "Genetic analysis of sporadic medullary thyroid carcinoma (MTC) has revealed somatic variants in RET, RAS, and occasionally other genes." (PMID 38655100, 2024). "Both RET variants had been previously reported in medullary thyroid carcinoma (MTC) and/or MEN2 but only the c.2410G>A (p.Val804Met) variant has been described in patients with isolated PCC." (PMID 39596125, 2024). "A recent investigation using the Examination Aggregation Consortium (ExAC) dataset estimated the penetrance of medullary thyroid carcinoma to be approximately 4% among RET variant (c.2410G > A), (p.Val804Met) carriers." (PMID 38802890, 2024). "Activating mutations in RET, however, are known to be oncogenic in medullary thyroid cancer (MTC), making this RET-altered tumour different than papillary thyroid cancer or non-small-cell lung carcinoma (NSCLC)." (PMID 37277734, 2023). "Among them, RET point mutation frequently occurred in multiple endocrine neoplasias and medullary thyroid carcinoma." (PMID 36865807, 2023). "On the other hand, a germ-line or somatic RET mutation was linked with more intense and complete angiogenesis in patients with advanced medullary thyroid cancers." (PMID 37228491, 2023). "Apart from amplification, the constitutive activation of RET is caused by point mutations and gene rearrangements that drive malignancy in multiple tissues (i.e., papillary and medullary thyroid carcinomas and non-small cell lung carcinomas)." (PMID 36839989, 2023). "The ATA has classified RET GPVs from those associated with the highest to moderate risk of medullary thyroid carcinoma." (PMID 37258796, 2023). "The incidence of RET/PTC rearrangement is about 15%–20% in sporadic PTC, and the positive rate of RET gene mutation is nearly 50% in patients with medullary thyroid cancer." (PMID 37081757, 2023). "Selpercatinib has exhibited robust and durable anti-tumor activity in medullary thyroid carcinoma (MTC) cases harboring RET mutations." (PMID 37375228, 2023). "Vandetanib, a multi-TKI including RET inhibition, was evaluated in association with bortezomib in 22 patients (17 evaluable cases) with medullary thyroid cancer, with 27% showing partial responses." (PMID 36839989, 2023). "This is an autosomal dominant syndrome associated with medullary thyroid cancer and arises due to a mutation in the RET proto-oncogene." (PMID 37251685, 2023). "Medullary thyroid cancer derives from calcitonin-producing C cells and is characterized by sporadic and familial RET-mutated forms." (PMID 37568824, 2023). "Recently, it was observed that pediatric tumors (soft tissue sarcomas or medullary thyroid cancer) harboring either an RET-fused or RET-mutated pathogenic somatic alteration show clinical response to the RET inhibitor Selpercatinib." (PMID 36839989, 2023). "Selpercatinib and pralsetinib, potent and selective receptor kinase inhibitors with activity against RET, have revolutionized the treatment paradigm for medullary thyroid cancers and other cancers with driver mutations in RET." (PMID 37434642, 2023). "Earlier multi-kinase inhibitors (MKIs) such as cabozantinib and vandetanib have been tested in clinical trials for the treatment of RET fusion-positive NSCLC or medullary thyroid cancers (MTCs) with RET mutations." (PMID 37743366, 2023). "RET point mutations are most commonly found in sporadic medullary thyroid cancer (MTC) and as germline mutations in multiple endocrine neoplasia syndrome (MEN)." (PMID 36557971, 2022).
medullary thyroid carcinoma (continued). "All germline RET carriers had known pathogenic variants previously associated with increased heritable risk of medullary thyroid cancer." (PMID 35304457, 2022). "Second, somatic or germline point mutations in the kinase domain of RET result in aberrant RET kinase activation, causing medullary thyroid cancer." (PMID 35304457, 2022). "MEN2-associated (RET) mutations are most often associated with medullary thyroid carcinoma, pheochromocytoma, and parathyroid tumors." (PMID 36428741, 2022). "The third RET M918T-mutant medullary thyroid cancer patient in whom we detected a gatekeeper V804M mutation at baseline subsequently developed an acquired Y806C mutation in cis." (PMID 35304457, 2022). "Selpercatinib, a RET kinase inhibitor, is an effective treatment for patients with medullary thyroid cancer with RET mutations." (PMID 35621672, 2022). "According to the 2015 American Thyroid Association Guidelines for the Management of Medullary Thyroid Carcinoma, patients with RET codon 634 mutations are at high risk." (PMID 35627249, 2022). "In the analyses of selpercatinib‐ or pralsetinib‐resistant patients with RET fusions (NSCLC or medullary thyroid cancer), several secondary mutations have been reported." (PMID 34997674, 2022). "Prophylactic and early thyroidectomy in RET germline mutation carriers allows the removal of the thyroid before medullary thyroid carcinoma (MTC) develops, or while it is still confined to the gland." (PMID 36551711, 2022). "We found that MEN2A patients with the RET c.1901G>A mutation tended to have bilateral PHEOs that appeared earlier than medullary thyroid carcinoma." (PMID 35627249, 2022). "RET (rearranged during transfection) variants are the most prevalent oncogenic event in medullary thyroid cancer (MTC)." (PMID 35884466, 2022). "In the current study, five cases had different pathogenic RET variants with different clinical presentations as pheochromocytoma, medullary thyroid cancer, and thyroid nodules." (PMID 33777662, 2021). "Germline mutations of the RET proto-oncogene generate hereditary medullary thyroid cancer, whereas somatic RET and RAS mutations were described in this sporadic disease." (PMID 34680488, 2021). "RET fusions occur in different types of cancers, including lung cancers (1–2%) and papillary thyroid cancers (10–20%), whereas RET mutations affect mostly medullary thyroid cancers (MTCs)." (PMID 34832869, 2021). "RET-inhibitors for RET-mutated medullary thyroid cancer (MTC) recently have been FDA-approved for metastatic disease." (PMID 33569345, 2021). "It has been reported that medullary thyroid cancer patients with RET germline mutations show higher STAT3 activation and its nuclear localization." (PMID 34207842, 2021). "Pathogenic germline variants in the protooncogene RET are responsible for the hereditary form and part of the apparently sporadic cases of medullary thyroid carcinoma (MTC), and a strong genotype-phenotype correlation has been observed for those variants." (PMID 34769224, 2021). "Although RET (rearranged during transfection) is the bona fide driver oncogene in hereditary medullary thyroid carcinoma, it has been suggested that the germline mutation of the cancer-predisposing gene does not trigger cancer per se." (PMID 33435319, 2021). "We detected codon 634 mutations in two cases (40%) of five RET-mutated cases—C634Y-mutated case had medullary thyroid cancer, and C634R-mutated case had pheochromocytoma." (PMID 33777662, 2021). "Germline mutations at codon 804 in RET are commonly identified in patients with multiple endocrine neoplasia type 2 and confer an elevated lifetime risk of medullary thyroid carcinoma." (PMID 33898318, 2021). "Broad-based tyrosine kinase inhibitors (TKI) such as cabozantinib are approved for the treatment of RET mutations (base substitutions) in medullary thyroid cancers occurring both in sporadic forms and as a component of the MENII syndromes." (PMID 34282751, 2021).
medullary thyroid carcinoma (continued). "Chromosomal rearrangement or point mutations in RET are observed in patients with papillary thyroid and medullary thyroid carcinomas." (PMID 33419162, 2021). "A previous study showed positive expression of SV2 in medullary thyroid carcinoma caused by a gain-of-function mutation in RET." (PMID 33561442, 2021). "Medullary thyroid cancer is a rare tumor originating from the parafollicular C cells of the thyroid, and it is characterized by RET proto-oncogene mutation in almost all hereditary cases and more than 40% of sporadic cases." (PMID 33777662, 2021). "Mutation of the proto-oncogene RET is common in medullary thyroid cancer, and RET protein is a substrate to HSP90-mediated protein folding and processing." (PMID 33228205, 2020). "Mutations in RET are identified in approximately 50% of patients with sporadic medullary thyroid carcinoma." (PMID 32993133, 2020). "Gain-of-function mutations in RET are associated with familial neuroendocrine tumours and medullary thyroid cancers." (PMID 33020210, 2020). "Genetic analysis for germline mutations of RET proto‐oncogene has provided a basis for individual management of medullary thyroid carcinoma (MTC) and pheochromocytoma." (PMID 32989896, 2020). "RET (REarranged during Transfection) is a proto-oncogene associated with medullary thyroid cancer containing a G4 forming sequence in its promoter." (PMID 30682828, 2019). "The oncogenic transforming role of germline RET mutations in hereditary medullary thyroid carcinoma (MTC) has been reported 25 years ago." (PMID 31510104, 2019). "Surprisingly, RET mutations, occurring mostly in medullary thyroid carcinoma, were one of the most common genetic events in both FTAs and FTCs." (PMID 31248021, 2019). "Consistent with the dominant occurrence of the RET-related tumors, somatic mutations are found in sporadic Medullary Thyroid Carcinoma (MTC)." (PMID 35582269, 2019). "We used population data to estimate unbiasedly penetrance of pathogenic RET mutations for medullary thyroid cancer, revealing that p.Val804Met is vastly less penetrant than other RET mutations at ∼4%." (PMID 29590403, 2018). "RET (REarranged during Transfection) proto-oncogene variants are essential for the development of familial and sporadic forms of medullary thyroid carcinoma (MTC)." (PMID 30072953, 2018). "EGFR mutation in non-small cell lung cancer (NSCLC), RET mutation in medullary thyroid carcinoma, ALK translocation and ROS1 translocation in NSCLC and HER2 amplification in breast cancer have been reported and therapies have been established." (PMID 30404198, 2018). "As already reported, medullary thyroid cancer (MTC) is characterized by RET hyperactivation, due to the presence of enzymatic mutated forms." (PMID 30423915, 2018). "Genetic testing for the RET gene variants was performed with standard methods in 585 people aged 1–85, including 448 patients with medullary thyroid carcinoma and 131 of their first- and second-degree relatives, as well as six patients suspected of MTC/MEN2." (PMID 28647780, 2017). "Gain-of-function germline mutations of the RET proto-oncogene are responsible for initiation of carcinogenesis within the thyroid gland and development of hereditary form of medullary thyroid carcinoma and MEN2 syndrome." (PMID 28647780, 2017). "Dominant-activating mutations in the RET proto-oncogene, a receptor tyrosine kinase, are responsible for the development of medullary thyroid carcinoma (MTC) and causative for multiple endocrine neoplasia (MEN) type 2A and 2B." (PMID 28122586, 2017). "In this study, we found a significant upregulation of miR-182 in tissues of a cohort of medullary thyroid carcinomas compared to normal thyroid tissue and in cell lines expressing RET mutations." (PMID 28122586, 2017). "Medullary thyroid cancer (MTC) can be caused by germline mutations of the RET proto-oncogene or occurs as a sporadic form." (PMID 28181547, 2017).
medullary thyroid carcinoma (continued). "Historically, BHD syndrome was first identified in a family who developed hereditary medullary carcinoma of the thyroid, a disease now recognized as a tumor-suppressor gene syndrome caused by a germline RET mutation." (PMID 27871249, 2016). "Activation of RET is a mechanism of oncogenesis in medullary thyroid carcinomas where both germline and sporadic activating somatic mutations are prevalent." (PMID 27429741, 2016). "Deregulation of the receptor tyrosine kinase RET has been implicated in medullary thyroid cancer, a small percentage of lung adenocarcinomas, endocrine-resistant breast cancer and pancreatic cancer." (PMID 26874741, 2016). "The RET S836S variant has been associated with early onset and increased risk for metastatic disease in medullary thyroid carcinoma (MTC)." (PMID 26829565, 2016). "Somatic mutations of the RET gene are also responsible for sporadic Medullary Thyroid Carcinoma (MTC), while gene rearrangements have been found in papillary thyroid carcinoma (PTC) and recently identified in lung adenocarcinoma." (PMID 27034161, 2016). "The application of TKi has recently expanded to RET-mutated medullary thyroid carcinoma, RET-translocated NSCLC and other solid tumors (NCT02183870, NCT0194502, NCT01823068, NCT01639508)." (PMID 26943776, 2016). "The gain-of-function mutation of the RET proto-oncogene, which encodes a receptor tyrosine kinase, is strongly associated with the development of several medullary thyroid carcinomas (MTCs)." (PMID 26307103, 2015). "RET oncogenic conversion is a hallmark of several human cancers, including papillary and medullary thyroid carcinoma, lung adenocarcinoma and chronic myelomonocytic leukemia." (PMID 26046350, 2015). "Accurate interpretation of germline mutations of the rearranged during transfection (RET) proto-oncogene is vital for the proper recommendation of preventive thyroidectomy in medullary thyroid carcinoma (MTC)-prone carriers." (PMID 25425582, 2015). "RET gain of function mutations and translocations are associated with the development of a variety of human cancers, including medullary thyroid carcinoma, multiple endocrine neoplasias (MEN) type 2A and 2B, pheochromocytoma, and parathyroid hyperplasia." (PMID 24466333, 2014). "For instance, the presence of hemangioblastomas (suggestive of von Hippel-Lindau) or medullary thyroid carcinoma along with pheochromocytoma (suggestive of MEN 2A) strongly implies mutations in VHL or RET gene, respectively." (PMID 24899893, 2014). "The mutation (Cys618Arg) in exon 10 of the oncogene RET is described as a mutation with a higher risk of developing a medullary thyroid cancer, so a prophylactic total thyroidectomy with central lymphadenectomy was performed 3 months after adrenalectomy." (PMID 25374962, 2014). "In total, 42 medullary thyroid carcinomas (MTC) were studied including 24 rearranged during transfection (RET)- mutated cases." (PMID 24758186, 2014). "RET rearrangements are common (30%) in papillary thyroid carcinomas, and mutations are found in 50% of medullary thyroid carcinomas." (PMID 24722523, 2014). "The RET gene is the oncogene that causes papillary thyroid carcinoma and medullary thyroid carcinoma which encodes a single-pass transmembrane receptor tyrosine kinase." (PMID 24376526, 2013). "It was stressed that patients carrying the same RET mutation present heterogenic progression to the clinically overt medullary thyroid cancer, even in the same family." (PMID 23514096, 2013). "Nowadays, RET point mutations are applied as markers for identifying hereditary and sporadic Medullary Thyroid Carcinoma (MTC)." (PMID 23815863, 2013). "In contrast, medullary carcinomas with sporadic RET mutations or with wild-type RET were observed with heterogeneous expression of AKT/mTOR pathway molecules, which suggests the need for further elucidation of alternative activation mechanisms." (PMID 23509459, 2013).
medullary thyroid carcinoma (continued). "Germ line gain-of-function RET mutations are associated with familial neuroendocrine tumours and medullary thyroid cancers; RET mutations are also found in sporadic medullary and papillary thyroid carcinoma." (PMID 23868506, 2013). "Germline mutations of RET are responsible for the development of heritable forms of medullary thyroid carcinoma (MTC), while somatic mutations of this oncogene are found in a significant proportion of sporadic MTCs." (PMID 23455356, 2013). "Mutations in the RET proto-oncogene have been implicated in the pathogenesis of several forms of medullary thyroid cancer (MTC)." (PMID 23455356, 2013). "RET point mutations were also found in medullary thyroid carcinoma (MTC), accounting for nearly all hereditary cases and about 50% of sporadic MTC." (PMID 23056499, 2012). "At the end of the 90s, the association of RET gene mutations with the occurrence of medullary thyroid carcinoma (MTC) and Multiple endocrine neoplasia type 2A (MEN 2A) was described." (PMID 23088776, 2012). "Multiple endocrine neoplasia 2A (MEN2A) is a rare autosomal dominant syndrome caused by missense mutations in the RET proto-oncogene associated with medullary thyroid cancer, pheochromocytoma and hyperparathyroidism." (PMID 21843357, 2011). "Calcitonin and thyroglobulin are markers for disease recurrence after surgical resection, and the RET point mutations are used to predict susceptibility and prognosis of a patient with familial medullary thyroid cancer." (PMID 24281099, 2010). "Mutations in the lamina A (LMNA) gene are linked to Progeria, while mutations in REarranged during transfection (RET) are linked to multiple endocrine neoplasia (MEN2A MEN2B) and medullary thyroid carcinoma (MTC)." (PMID 21358990, 2010). "The hereditary RET point mutations are the most specific biomarkers in clinical use today for diagnosing patients who will develop medullary thyroid cancer." (PMID 24281099, 2010). "The single known inheritable gene mutation associated with thyroid cancer is a point mutation in the RET proto-oncogene that causes medullary thyroid cancer." (PMID 24281099, 2010). "A 2009 study reported the presence of RET oncogene mutations in human medullary thyroid cancer cell lines (TT and MZ-CRC-1) based on proteomic analysis and antibody-based validation techniques." (PMID 24281099, 2010). "Point mutations of the RET gene that cause medullary thyroid cancer result in a gain of function of the RET receptor." (PMID 24281099, 2010). "Multiple individual RET gene point mutations have been identified and have led to the genotype-phenotype correlation of RET mutations and the stratification of hereditary medullary thyroid cancer into three risk groups (Levels 1, 2, and 3)." (PMID 24281099, 2010). "Screening of REarranged during Transfection (RET) gene mutations has been carried out in different series of sporadic medullary thyroid carcinomas (MTC)." (PMID 19401695, 2009). "The present case of a collision tumor, displaying a unique G691 polymorphism, is suggestive of additional genetic modifiers of RET gene mutations in cases of sporadic medullary carcinoma thyroid." (PMID 17939859, 2007). "RET point mutations can also occur as a somatic event in sporadic medullary thyroid carcinomas and pheochromocytomas." (PMID 17683521, 2007). "Activating point mutations of RET proto-oncogene have been demonstrated to be causative of the familial form of medullary thyroid cancer, both as isolated FMTC and associated to MEN 2A and 2B." (PMID 17997826, 2007). "Recently, we successfully used a double tandem hybridization strategy in the genesensor chip system to discriminate point mutations in codon 634 of RET oncogene in individuals affected by medullary thyroid carcinoma." (PMID 15713227, 2005). "Medullary thyroid cancer has a five-year survival rate of approximately 75-80% and is strongly associated with genetic predisposition, with some patients carrying mutations in the RET proto-oncogene." (PMID 39980569, 2025).